VN1R10P (vomeronasal 1 receptor 10 pseudogene)
Synonyms: hs6V1-1p; b24o18.2; formerly VNR6I1P
Gene: Unprocessed pseudogene on chromosome 6 (27,324,894 to 27,325,768, forward strand). Ensembl gene ENSG00000220758.
Diseases named in the same sentence as VN1R10P in open-access papers:
VN1R10P is named in the same sentence as 5 diseases in open-access papers, as found by Europe PMC text mining. Sharing a sentence is not in itself a finding about the gene and the disease.
VN1R10P shares sentences with these, for which no sentence is quoted: Hepatic steatosis (1 paper); nonalcoholic fatty liver disease (1); primary sclerosing cholangitis (1); rheumatoid arthritis (1); Sjogren syndrome (1).